TMSB10 (thymosin beta 10)
Diseases named in the same sentence as TMSB10 in open-access papers (continued):
Sharing a sentence is not in itself a finding about the gene and the disease.
tumor (continued). "Furthermore, we verified that hybrid cells within the primary tumor and in peripheral blood express TMSB10, CD74 and GPX1 at the protein level, and that TMSB10 and GPX1 are significantly upregulated in disseminated hybrid cells compared to CTCs." (PMID 38106024, 2023). "In order to further understand the role of TMSB10 in predicting the efficacy of Immune Checkpoint Inhibitor (ICI), we used Tumor Mutation Burden (TMB) and Microsatellite Instability (MIS) to predict the relationship between TMSB10 and the efficacy of immunotherapy." (PMID 37275863, 2023). "By contrast, TMSB10 is lowly expressed in 3 tumor types: KICH、LIHC and PRAD (all P<0.05)." (PMID 37275863, 2023). "Our results show that TMSB10 is abnormally expressed in tumor tissues, which may be related to the infiltration of immune cells in the tumor microenvironment." (PMID 37275863, 2023). "TMSB10 may exert its function in the development and progression of cancer by regulating tumor microenvironment and mediating tumor-related immune and inflammatory responses." (PMID 37275863, 2023). "Additionally, TMSB10 expression exhibited correlations with immune cell infiltration, suggesting its potential influence on the tumor immune microenvironment." (PMID 38026448, 2023). "Western blot results also showed that knockdown of TMSB10 increased the expression of P21 (a tumor suppressor protein) but decreased the expression of carcinogenic proteins involved in cell proliferation and invasion and the result was consistent in mice tumor samples." (PMID 36163046, 2022). "Additionally, in vivo experiments also showed that the downregulation of TMSB10 significantly reduced tumor size and prolonged the survival time of tumor-bearing mice." (PMID 36163046, 2022). "Together, these studies indicated that decreased expression of TMSB10 promotes tumor growth." (PMID 36109592, 2022). "Furthermore, we found that the expression of TMSB10 in the tumor tissues was the highest among these seven TMSs, and TMSB15A, TMSB4Y and TMSB15B showed relatively low expression." (PMID 36163046, 2022). "High TAMs-associated TMSB10 expression was significantly associated with advanced TNM stage (P = 0.036) and T3/T4 tumor size (P = 0.007), indicating TAMs-associated TMSB10 might contribute to tumor proliferation or metastasis." (PMID 33349268, 2020). "Moreover, we identified tumor stage (P=0.009), tumor size (P=0.039), distant metastasis (P<0.001), and TMSB10 expression (P<0.001) as prognostic factors for overall survival in HCC patients through univariate Cox proportional hazards regression analysis." (PMID 30787051, 2019). "TMSB10 immunohistochemical staining was observed only in the cytoplasm of tumor cells." (PMID 30787051, 2019). "In conclusion, TMSB10 may hold promise as a tumor biomarker for predicting prognosis and a potential target for developing a novel therapeutic strategy." (PMID 30787051, 2019). "On IHC the TMSB10 overexpressing tumor tissues had higher Ki67 proliferation indexes, whereas the TMSB10-silenced tumor tissues had reduced numbers of Ki67-positive cells, which is consistent with the results of analysis of clinical correlation between TMSB10 and Ki67." (PMID 28179017, 2017). "Prior research has established that TMSB10 can facilitate the transformation of tumor-associated macrophages (TAMs) into the M2 phenotype and enhance their proliferation via the PI3K/Akt signaling pathway, ultimately fostering tumor progression within the tumor microenvironment." (PMID 38795225, 2024). "Consequently, it is suggested that TMSB10 may have a significant involvement in the immune evasion and tumor advancement of ccRCC." (PMID 38795225, 2024). "Clinically, TMSB10 is not only an effective prognostic factor for predicting the clinical treatment outcome of cancer patients, but also a promising biomarker for predicting the effect of tumor immune checkpoint inhibitors (ICIs) and chemotherapy in some cancers." (PMID 37275863, 2023).
tumor (continued). "In addition, TMSB10 is closely associated with various tumor phenotypes such as cell proliferation, apoptosis, and angiogenesis, while overexpressed in HCC tissues and can affect distant tumor metastasis." (PMID 37006257, 2023). "TMSB10 may become a novel target for tumor immunotherapy and chemotherapy." (PMID 37275863, 2023). "Therefore, we speculate that TMSB10 promotes the metastasis of tumor cells probably by inhibiting RAS-related proteins and actin polymerization, leading to the loss of cell–cell junctions, cell polyrization and cell-ECM contacts." (PMID 28179017, 2017). "We further verify that expression of three genes identified from our scRNA-seq analyses, thymosin beta 10 (TMSB10), CD74 and GPX1, are expressed at the protein level in hybrid cells within patient-matched primary tumor and peripheral blood." (PMID 38106024, 2023). "Silenced DNMT1 or upregulated miR‐152‐3p reduced TMSB10 expression and suppressed CRC progression and tumor growth." (PMID 32918845, 2020). "In conclusion, TMSB10 expression is relatively high in HCC tissues, and correlated with the advanced tumor stage and distant metastasis in HCC patients." (PMID 30787051, 2019). "In addition, there were strong positive associations between TMSB10 expression and clinical stage, tumor (T) classification, node (N) classification, metastasis (M) classification, pathological grade, estrogen receptor (ER) status and progesterone receptor (PR) status." (PMID 28179017, 2017). "We further verify that expression of three genes identified from our scRNA-seq analyses, thymosin beta 10 (TMSB10), CD74 and GPX1, are expressed at the protein level in hybrid cells within patient-matched primary tumor and peripheral blood (n = 4; n = 1 GEP class 1 and n = 3 GEP class 2)." (PMID 39030653, 2024). "Additionally, TMSB10 has been indicated to be overexpressed in RCC, promoting the tumor cell malignant metastasis by inducing EMT, which was consistent with our data." (PMID 38035023, 2023). "Both TMSB10 and GPX1 were expressed on significantly higher numbers of disseminated hybrid cells compared to circulating tumor cells, and CD74 and GPX1 were expressed on more disseminated hybrids than tumor-resident hybrids." (PMID 38106024, 2023). "In addition, an interesting study published in 2005 showed that TMSB10 hindered RAS-RAF interaction, thereby suppressing the RAS/ERK signaling pathway as well as angiogenesis and tumor growth." (PMID 36109592, 2022). "TMSB10 and TMSB4X expression were higher in patients with the C2 and C6 subtypes, which indicate a poorer prognosis, suggesting that TMSB10 and TMSB4X might be involved in tumor immune deregulation." (PMID 36163046, 2022). "TMSB10 was highly upregulated in cluster 9 ECs, and is involved in facilitating the expression of VEGF signaling factors, indicating that cluster 9 ECs may be related to the promotion of cytoskeleton formation and tumor angiogenesis in tumor tissues." (PMID 37533434, 2023). "To further explore the biological processes of TMSB10 in cancer initiation and development, we performed Gene Set Variation Analysis (GSVA) on 33 cancers to evaluate the relationship between TMSB10 and 50 common cancer signaling pathways, tumor immune and inflammatory responses." (PMID 37275863, 2023). "TMSB10 expression level positively correlated with the AKT-activated gene signatures but negatively correlated with the FOXO(s)-activated gene signatures, suggesting that the AKT/FOXO pathway may mediate the pro-tumor effects of TMSB10." (PMID 28179017, 2017).
cancer (22 papers, 2001 to 2026). A tumor composed of atypical neoplastic, often pleomorphic cells that invade other tissues. "Some markers CD14 (monocyte), CD3D (CD4+T cells), CD3E (CD8+T cells), CD68 (macrophage), CST3 (myeloid cells), GNLY (NK cells), KRT18 (epithelial cells), and NKG7 (NK cells) were positively associated with TMSB10 in all cancers." (PMID 37275863, 2023). "Previous studies have implicated TMSB10 in various cancer types, including breast, colorectal, lung, and renal cancers." (PMID 38026448, 2023). "There is ample evidence suggesting that TMSB10 is one of the key regulators of malignancy and metastasis in various types of cancers and PM and DM are well-known for its association with malignancy." (PMID 31671645, 2019). "Moreover, the inhibition of ccRCC cell proliferation, migration, and invasion was observed in cell culture upon knocking down TMSB10, a gene associated with different types of cancers." (PMID 38795225, 2024). "Further gene enrichment analysis using Cytoscape dayabase revealed that genes that were significantly positively associated with TMSB10 were significantly enriched in immune-related, stromal activation-related and cancer malignant progression-related signaling pathways." (PMID 36163046, 2022). "Aberrant TMSB10 expression has been implicated in the pathogenesis of human cancer." (PMID 28179017, 2017). "This study initially analyzed the differential expression of TMSB10 in TCGA pan-cancer samples compared to corresponding normal tissues." (PMID 40307738, 2025). "The finding underscores the potential role of TMSB10 in tumorigenesis and suggests its viability as a promising target for therapeutic interventions across various cancer subtypes." (PMID 38795225, 2024). "A robust correlation has been identified between TMSB10 and the infiltration of immune cells, while the exploration of TMSB10's role in the domain of cancer biology remains limited." (PMID 38795225, 2024). "The discovery underscores the potential significance of TMSB10 as a prognostic indicator for patient results in different forms of cancer, while also underscoring its therapeutic targeting possibilities." (PMID 38795225, 2024). "The relationship between TMSB10 expression and various immune cell infiltration in pan-cancer was explored by TIMER2.0 database." (PMID 37275863, 2023). "Pan-cancer analysis showed that TMSB10 was differentially expressed in most cancers, most of which were highly expressed." (PMID 37669296, 2023). "Although many studies have supported that TMSB10 promotes macrophage M2 conversion and serves as a biomarker in cases with malignant tumors, few studies have investigated its specific role in DMD cases." (PMID 35720684, 2022). "We further comprehensively evaluated the expression pattern, biological function and immunological role of TMSB10 across 33 cancers." (PMID 36163046, 2022). "Regarding the function of TMSB10, experiments using human cancer cell lines showed that the protein binds directly to RAS, and thereby suppresses RAS-RAF interaction." (PMID 36109592, 2022). "Although the functions of TMSB10 in cancer cells remain controversial, these findings regarding the potential of TMSB10 to regulate signal pathways showed that it has functions beyond those related to actin sequestration." (PMID 36109592, 2022). "The results showed that TMSB10 was specifically overexpressed in almost all types of cancer tissues, and we further comprehensively evaluated the expression pattern, biological function and immunological role of TMSB10 across cancers." (PMID 36163046, 2022). "TMSB10 had significant prognostic value in the largest number of cancer types, acting as an adverse prognostic factor in nine cancer types." (PMID 36163046, 2022). "We comprehensively assessed genomic mutations, expression dysregulation, prognosis and immunotherapeutic response across 33 human cancer samples and showed that TMSB10 is specifically overexpressed in almost all types of cancer tissues." (PMID 36163046, 2022).
cancer (continued). "TMSB10 also has been proven to be overexpressed in most human solid tumors, and regulate cancer cell proliferation and metastasis." (PMID 33349268, 2020). "TMSB10 has been demonstrated to be overexpressed in most types of human cancer, and participate in regulating cell proliferation and motility." (PMID 30787051, 2019). "The roles of TMSB10 have been investigated using various human cancer tissues compared with normal tissues in recent years, and it has been identified as a reliable cancer biomarker." (PMID 29921287, 2018). "Thymosin beta 10 (TMSB10) has been demonstrated to be involved in the malignant process of many cancers." (PMID 28179017, 2017). "TMSB10 is upregulated in multiple human cancers and upregulation of TMSB10 contributes to cancer cell proliferation, migration and invasion via different mechanisms, and predicts poor survival." (PMID 28179017, 2017). "However, in kidney chromophobe (KICH), TMSB10 expression was significantly higher in normal tissues than in other cancer types (P < 0.0001)." (PMID 40307738, 2025). "This research also provides a foundation for further exploration of TMSB10’s role in other cancers." (PMID 40307738, 2025). "Then, we analyzed the clinical prognostic with the expression level of TMSB10 in 33 cancers." (PMID 37275863, 2023). "In view of the abnormal expression of TMSB10 in pan-cancer, we speculate that this phenomenon may be related to the genetic alteration of TMSB10." (PMID 37275863, 2023). "In our study, we proved that TMSB10 could become a hopeful prognosis biomarker in pan-cancer, especially in the response of cancer immunotherapy and chemotherapy in the future." (PMID 37275863, 2023). "High expression of TMSB10 could predict a poor prognosis in 19 cancers, and low expression of TMSB10 could predict a positive prognosis in 5 cancers." (PMID 37275863, 2023). "TMSB10 may be used as an effective marker to predict the efficacy of immune checkpoint inhibitors in some cancer." (PMID 37275863, 2023). "We retrieved The Cancer Genome Atlas and Genotype-tissue expression datasets to obtain the difference of TMSB10 expression between pan-cancer and normal tissues, and analyzed the biological function and prognosis role of TMSB10 in pan-cancer by using cBioPortal Webtool." (PMID 37275863, 2023). "In our study, we conducted a pan-cancer genomic analysis of TMSB10 across different cancer types by using GTEx and The Cancer Genome Atlas (TCGA) database, evaluating the expression of TMSB10 and its association with the prognosis of patients with different cancers." (PMID 37275863, 2023). "Previous study also explored the function roles of TMSB10 in pan-cancer." (PMID 37275863, 2023). "TMSB10 transcriptional factor is involved in cytoskeleton organization and cancer cell migration." (PMID 36500393, 2022). "Most studies showed that knockdown of TMSB10 reduced cancer cell proliferation or migration." (PMID 33349268, 2020). "Thymosin beta 10 (Tbeta10) overexpression has been reported in a variety of human cancers." (PMID 25037578, 2014). "Additionally, TMSB10 functions may vary across different cancer types, and its broader oncogenic role warrants further investigation." (PMID 40307738, 2025). "Therefore, we hypothesized that TMSB10 could be an effective biomarker to predict the efficacy of immune checkpoint inhibitors in pan-cancer." (PMID 37275863, 2023). "Notably, the expression and function of TMSB10 across cancers, including its involvement in immune-related processes, remain largely unknown." (PMID 36163046, 2022). "In cancers like BRCA, COAD, LUAD, and PRAD, TMSB10 expression positively correlated with TMB and MSI." (PMID 40307738, 2025). "The expression of TMSB10 and TMSB4X was positively correlated with the immune/stromal score in most cancer types." (PMID 36163046, 2022).
cancer (continued). "Curcumin was also found to effectively inhibited TYB10 (TMSB10) and TMSB4 (TYB4), where supressing their expression was reported to inhibit proliferation, migration, and invasion features of cancer cells." (PMID 33670440, 2021).
TMSB10 also shares sentences with these, for which no sentence is quoted: tuberculosis (9 papers); infection (8); gastric cancer (4); thyroid cancer (4); lung squamous cell carcinoma (2); pulmonary TB (2); Alpha-thalassemia (1); anemia (1); bipolar disorder (1); bovine tuberculosis (1); breast invasive carcinoma (1); breast tumors (1); co-infection (1); colon adenocarcinoma (1); colon cancer (1); Diamond-Blackfan anemia (1); endometriosis (1); endothelial dysfunction (1); ependymoma (1); esophageal cancer (1); Fanconi anemia (1); head and neck squamous cell carcinoma (1); influenza (1); liver diseases (1); lymph node metastasis (1); major depression (1); medulloblastoma (1); metastatic melanoma (1); microcytic anemia (1); non-small cell lung carcinoma (1).
A further 15 diseases each share a sentence with TMSB10 in 1 paper.